RN7SL810P (RNA, 7SL, cytoplasmic 810, pseudogene)
Gene: Miscellaneous RNA gene on chromosome 13 (77,947,497 to 77,947,772, reverse strand). Ensembl gene ENSG00000243035.
Homologues: Orthologues: chimpanzee Metazoa_SRP (99% identical). Paralogues in human: RN7SL2 (79% identical), RN7SL1 (78% identical), RN7SL122P (78% identical), RN7SL3 (78% identical), RN7SL220P (77% identical), RN7SL478P (77% identical), RN7SL543P (77% identical), RN7SL709P (77% identical), RN7SL296P (77% identical), RN7SL408P (76% identical), RN7SL556P (76% identical), RN7SL743P (76% identical), and 700 more.